DEFB106A (defensin beta 106A)
Description:
Has antibacterial activity. Acts as a ligand for C-C chemokine receptor CCR2.
Synonyms: BD-6; DEFB-6; DEFB106
Tractability: Antibody: UniProt places it where antibodies can reach, with high confidence; UniProt predicts a signal peptide or a membrane-spanning region; its Gene Ontology location is reachable by antibodies, with medium confidence.
Gene: Protein-coding gene on chromosome 8 (7,825,139 to 7,829,053, forward strand). Ensembl gene ENSG00000186579.
Subcellular location: Secreted; Membrane
Pathways (Reactome):
Immune System: Beta defensins; Defensins
Gene Ontology:
Molecular function: CCR2 chemokine receptor binding; heparin binding; lipopolysaccharide binding; protein binding
Biological process: antifungal innate immune response; defense response to Gram-negative bacterium; defense response to Gram-positive bacterium; innate immune response
Cellular component: membrane; microvesicle; nucleus; extracellular region
Homologues: Orthologues: chimpanzee DEFB106A (100% identical). Paralogues in human: DEFB106B (100% identical).